ENSG00000286143 (novel protein)
Gene: Protein-coding gene on chromosome 2 (219,491,867 to 219,498,244, forward strand). Ensembl gene ENSG00000286143.
Genetic constraint (gnomAD): Loss-of-function variants: 21 observed, 29.9 expected, observed/expected ratio (o/e) 0.7, 90% interval 0.5 to 1.01. Missense variants: 351 observed, 391.2 expected, observed/expected ratio (o/e) 0.9, 90% interval 0.82 to 0.98. Synonymous variants: 154 observed, 155.97 expected, observed/expected ratio (o/e) 0.99, 90% interval 0.87 to 1.13.